RCOR2 (REST corepressor 2)
Diseases named in the same sentence as RCOR2 in open-access papers (continued):
Sharing a sentence is not in itself a finding about the gene and the disease.
tumor (continued). "GSCALite analysis showed that each member of RCORs exhibited different activation or inhibition in common signaling pathways, indicating that RCOR1, RCOR2, RCOR3 probably work independently or competitively in tumor progression so that leading to opposite effect on the prognosis of cancer patients." (PMID 37342230, 2023). "Moreover, RCOR2 binds and activates LSD1, a histone lysine demethylase recently identified as a potent inhibitor of anti-tumor immunity." (PMID 32117236, 2020). "Notably, genetic deletion of CD4+ T cells greatly promoted MC38 tumor growth and abolished tumor reduction conferred by RCOR2 KO in mice, supporting an inhibitory role of CD4+ T cells in RCOR2-induced tumor growth, either directly or indirectly through their regulation of other immune components." (PMID 40608411, 2025). "RCOR2 was significantly upregulated in UCEC tissues at both mRNA and protein levels, and its expression correlated with key clinical features including advanced stage, higher histologic grade, and lymph node metastasis, suggesting its involvement in tumor progression." (PMID 40936699, 2025). "RCOR2 could activate LSD1, recently identified as a potent inhibitor of anti-tumor immunity." (PMID 35125116, 2022). "RCOR1 and RCOR2 expression differed significantly among tumor stages, whereas no significance exists between RCOR3 expression and tumor stages, we still noticed that RCOR3 expression elevated progressively among stage II, III, and IV." (PMID 37342230, 2023).
cancer (5 papers, 2020 to 2025). A tumor composed of atypical neoplastic, often pleomorphic cells that invade other tissues. "RCOR2 loss potentiated anti–PD-1 therapy in mouse models of cancer and correlated with better response to anti–PD-1 therapy in human patients." (PMID 40608411, 2025). "Additionally, RCOR2 has been implicated in the regulation of immune responses, further suggesting its potential role in tumorigenesis and cancer progression." (PMID 40936699, 2025). "Notably, loss of RCOR2 robustly improves anti–PD-1 blockade therapy in mouse models of cancer." (PMID 40608411, 2025). "Collectively, these findings uncover a “two birds with one stone” effect for RCOR2, highlighting its potential as a valuable target for improved cancer therapy." (PMID 40608411, 2025). "RCOR2 activates Wnt/β-catenin signaling but suppresses CIITA/MHC-II signaling in cancer cells through two distinct epigenetic programs." (PMID 40608411, 2025). "Collectively, these results indicate that RCOR2 is strongly expressed in ALDHhi BCSCs and is sufficient and necessary for cancer cell plasticity." (PMID 40608411, 2025). "Preliminary bioinformatics analyses have indicated that RCOR2 is overexpressed in various cancers, including UCEC." (PMID 40936699, 2025). "The future development of a specific small-molecule inhibitor of RCOR2 has the potential to revolutionize cancer treatment regimens." (PMID 40608411, 2025). "In this study, we use a genetic approach to establish proof-of-concept that targeting RCOR2 can achieve a “two birds with one stone” effect for the better treatment of cancers." (PMID 40608411, 2025). "As such, RCOR2 is a central regulator that integrates cancer cell–intrinsic plasticity signals and extrinsic immune surveillance signals in tumors." (PMID 40608411, 2025). "Protein levels of CIITA and MHC-II molecules were also elevated in RCOR2-depleted cancer cells following IFN-γ treatment and in PyMT tumors, as shown by immunoblot, flow cytometry, and/or immunostaining assays." (PMID 40608411, 2025). "Together, these clinical studies in cancer patients strongly support RCOR2’s role in evading CD4+CD8+ T cell surveillance." (PMID 40608411, 2025). "Together, these findings indicate that RCOR2 specifically induces MHC-II silencing in cancer cells through suppression of CIITA." (PMID 40608411, 2025). "RCOR2 was established to be functional in cancer stem cells, where it positively regulates stemness gene expression." (PMID 35994213, 2022). "This suggests that RCOR2 may promote cancer cell survival and proliferation by modulating key signaling pathways." (PMID 40936699, 2025). "By searching differentially expressed genes involved in interferon signaling pathways from our RNA-Seq dataset, we found that a family of MHC-II heavy chain genes and their transcriptional coactivator CIITA were repressed by RCOR2, which was validated in multiple cancer cell lines by RT-qPCR assay." (PMID 40608411, 2025). "Targeting RCOR2 potentiated ICB therapy in mouse models of cancer." (PMID 40608411, 2025). "RCOR2 has been shown to regulate the expression of genes involved in cell cycle progression, apoptosis, and differentiation, all of which are crucial processes in cancer development and progression." (PMID 40936699, 2025). "Next, we studied whether RCOR2 controls activation of Wnt/β-catenin signaling in cancer cells." (PMID 40608411, 2025). "Recent studies have provided insights into the mechanisms by which RCOR2 may contribute to cancer." (PMID 40936699, 2025). "Consistently, RCOR2 inversely correlated with CIITA and most MHC-II heavy chain genes in 1,156 cancer cell lines and 1,210 pan-cancers." (PMID 40608411, 2025). "Collectively, these results indicate that RCOR2 is a valuable therapeutic target and biomarker that can predict a response to anti–PD-1 ICB in cancers." (PMID 40608411, 2025).
cancer (continued). "According to our study, in HCC, we extracted RCORs-miRNA-lncRNA pairs, such as RCOR1-hsa-miR-9-3p-CT62, RCOR2-hsa-miR-1343-3p-LINC02693, RCOR3-hsa-miR-128-3p, etc., offering potential targets for cancer therapy." (PMID 37342230, 2023). "Thus, that RCOR2 was discovered as a top CulPRIT may indicate that the transcriptional upregulation of RCOR2 in tumors confers a selective advantage via LSD1-mediated immune evasion—a mechanism with likely relevance to many cancer types according to our findings." (PMID 32117236, 2020). "We further show that HDAC1 and HDAC2, but not LSD1, are responsible for RCOR2-dependent transcriptional suppression of CIITA in cancer cells." (PMID 40608411, 2025). "Besides, both RCOR1 and RCOR3 displayed highest expression in LAML, whereas RCOR2 was obviously upregulated in UCS and LGG, indicating that RCORs expression may varied among different cancer types." (PMID 37342230, 2023).
RCOR2 also shares sentences with these, for which no sentence is quoted: colorectal tumors (1 paper); intervertebral disc degeneration (1); leukemia (1); triple-negative breast carcinoma (1).